INS (insulin)
Diseases named in the same sentence as INS in open-access papers (continued):
Sharing a sentence is not in itself a finding about the gene and the disease.
Hyperglycemia (continued). "Patients that were eating and had hyperglycemia at bedtime, supplemental rapid or short-acting insulin was recommended as follow: two units for BG 250–350 mg/dL (13.9–19.4 mmol/L) and four units for BG more than 350 mg/dL (more than 19.4 mmol/L)." (PMID 26697118, 2015). "Fetal insulin levels during exposure to maternal diabetes are often elevated due to the fetal beta-cell response to hyperglycemia." (PMID 26064981, 2015). "Intravenous (IV) insulin therapy with subcutaneous (SC) insulin is the mainstay of treatment in management of Hyperglycemia in hospitalized patients and has shown to improve morbidity and reduce mortality rates in critically ill patients." (PMID 25874191, 2015). "The excessive accumulation of intrahepatic triglycerides gradually attenuates the ability of insulin to suppress hepatic gluconeogenesis and triglyceride synthesis, resulting in the development of hyperglycemia, hyperinsulinemia and dyslipidemia." (PMID 26439744, 2015). "In comparison, fat-specific PPAR γ knockout animals showed complete lipoatrophy, impaired adipokine secretion, profound insulin resistance and hyperglycemia, abnormal bone, mammary gland and skin metabolism." (PMID 25825681, 2015). "In T1D, hyperglycemia occurs as a result of destruction of insulin-producing pancreatic β-cells in an autoimmune process." (PMID 26300887, 2015). "The attenuation of the response of insulin target tissues to the physiological actions of insulin leads to a compensatory increase in pancreatic insulin production in an attempt to reestablish glucose homeostasis and thus overt hyperglycemia." (PMID 26720346, 2015). "Our data show that the human GLP-1 analogue liraglutide improves hyperglycemia concomitantly with increased beta cell mass and insulin secretion when administered daily for 30 days to alloxan-induced diabetic mice." (PMID 25938469, 2015). "It is not known if results can be generalized to offspring exposed to more extreme intrauterine hyperglycemia or insulin treatment." (PMID 26361494, 2015). "ADMSCs injected by I.Sp route reverted hyperglycemia in 70% of diabetic treated mice, stimulating insulin production by pancreatic β cells." (PMID 25884215, 2015). "This reduction in hyperglycemia was associated with a 70% reduction in plasma corticosterone and ACTH concentrations but occurred independently of any change in plasma insulin, glucagon, epinephrine, norepinephrine or growth hormone concentrations." (PMID 25916467, 2015). "After initial rapidly corrected hyperglycaemia by continuous subcutaneous insulin infusion (CSII) for 7 d, a 4–6-day premixed insulin titration period subsequently followed." (PMID 26640487, 2015). "Consistent with ATP’s controlling glucagon and insulin secretion during hypo- and hyperglycemia, respectively, the dose-response relationship for glucose-induced [ATP]pm generation was left shifted in α-cells compared to β-cells." (PMID 25911612, 2015). "The present study also presents the fact that a certain dose of metformin not only ameliorates hyperglycemia and hyperlipidemia, but also improves insulin level." (PMID 26075281, 2015). "Insulin levels measured at the time of hyperglycemia (BGL 11.3 mmol/L) and before insulin treatment were undetectable (<2 mU/L), with low C peptide level of 0.1 nmol/L, beta-hydroxybutyrate 0.09 mmol/L and free fatty acids 0.11 mmol/L." (PMID 26631065, 2015). "The administration of MSCs promoted hyperglycemia reversion, pancreatic islet repair, insulin production improvement, regulatory T (Treg) cell expansion and inflammatory process reduction in MSC-treated diabetic animals." (PMID 25884215, 2015). "The causes and risk conditions of type 2 diabetes (T2D) are manifold, but on the molecular level they all lead to impaired insulin signalling and/or insulin secretion ultimately resulting in hyperglycaemia." (PMID 26018950, 2015).
Hyperglycemia (continued). "The insulin resistant obese condition was developed in week 4, along with hyperglycemia, hyperinsulinemia, and increased C-peptide, together with increased body weight, fat weight, and adiposity index." (PMID 25821506, 2015). "Dipping back to the Seventies, biochemists already taught us that exposure of Nickel in animal models induces insulin overload, glycogenolysis and hyperglycemia in a concentration dependent manner." (PMID 25822975, 2015). "It is well established that hyperglycemia in mice results in altered expression of β-cell transcription factors and defective insulin secretion, a situation described as β-cell dedifferentiation." (PMID 25982967, 2015). "This was further complicated by the toxicity, including hyperglycemia, which largely results from the overlap between IGF and insulin signaling systems and associated feedback mechanisms." (PMID 26217584, 2015). "Development of T2D is initially characterized by decreased insulin sensitivity, manifested by ensuing hyperglycemia and a compensatory response where pancreatic β-cells produce and secrete more insulin, which in turn results in hyperinsulinemia." (PMID 26085100, 2015). "We previously reported that the increase of SOCS3 and TNFα, in hyperglycemia, is associated with increased levels of IRS-1Ser307 phosphorylation and decreased phosphorylation of IRTyr1150/1151, leading to inhibition of normal insulin signaling." (PMID 25888955, 2015). "Hyperglycemia management using the current gold standard of therapy, insulin, improves morbidity in hospitalized patients." (PMID 28702223, 2015). "Under normal physiological circumstances, fatty acids and hyperglycemia increase insulin secretion that offsets hyperglycemia by increasing muscle glucose uptake, inhibiting hepatic glucose output, and decreasing lipolysis." (PMID 26106623, 2015). "DM is a complex metabolic disorder, characterized by high blood glucose levels (hyperglycaemia) and impaired lipid, carbohydrate and protein metabolism as a result of defects in insulin secretion, insulin action or both." (PMID 26577219, 2015). "Correction dose was combined with prandial insulin dose to compensate for hyperglycemia before meals." (PMID 26697118, 2015). "Hyperglycemia was also found to be an independent risk factor for electrophysiological and clinical signs of ICUAW, and increasing insulin dose reduced signs of ICUAW." (PMID 26242743, 2015). "T2D rats underwent persistent hyperglycemia, accompanied by significant reduction of serum insulin and C-peptide levels." (PMID 26379190, 2015). "PI3K signaling disrupts insulin signaling, and hyperglycemia has been considered a toxicity of PI3K inhibition." (PMID 26510909, 2015). "T2DM is a multifactorial metabolic disease mainly characterized by hyperglycemia, but before the occurrence of overt hyperglycemia, peripheral insulin resistance leads to compensatory insulin hypersecretion by pancreatic islets." (PMID 25821466, 2015). "MEA intake ameliorated hyperglycemia in diabetic mice via lowering glucose level and increasing insulin level." (PMID 26633490, 2015). "Clinical history regarding duration of illness, type and dose of insulin, and recent symptoms of hypoglycemia/hyperglycemia were recorded." (PMID 26494998, 2015). "Treatment of hyperglycemia immediately after transplant is generally initiated with and often requires an intravenous insulin infusion algorithm with frequent glucose monitoring." (PMID 25721247, 2015). "Reduced levels of IRS2 in humans have been proposed to lead to desensitized insulin/cytokine signalling and thus to hyperglycemia/muted immune responses, with prolonged IRS2 deficits exacerbating islet cell mass reduction leading to T2DM." (PMID 26178806, 2015). "Hyperglycemia induced by the intake of these beverages and foods stimulates high insulin secretions, which act per se as a growth factor and induce an increase of IGF-1 (insulin-like growth factor)." (PMID 26649040, 2015).
Hyperglycemia (continued). "Hyperglycemia can be controlled by the administration of insulin which suppresses glucose production and augments glucose utilization." (PMID 26561797, 2015). "On day 2 hyperglycemia (415 mg/dL) occurred, requiring continuous insulin infusion along with parenteral nutrition with glucose rates around 5-6 mg/Kg/min." (PMID 26770845, 2015). "Diabetes is a chronic metabolic disease of hyperglycemia resulting from defects in insulin secretion, action, or both." (PMID 25898945, 2015). "Several clinical studies with IV infusion of short acting insulin have shown reduced morbidity and mortality in hospitalized patients with hyperglycemia." (PMID 25874191, 2015). "Simplistically, prediabetes is inefficient processing of intracellular glucose, which leads to insulin resistant cells, hyperinsulinemia (increased insulin), and hyperglycemia (increased blood glucose levels)." (PMID 25866793, 2015). "The beta cell dysfunction results in unmet relative insulin need to maintain optimal glycemic control and in combination with insulin resistance at the periphery synergistically contributes to the long-term hyperglycemia." (PMID 26652175, 2015). "Ex-4 is an antidiabetic agent, which reduces hyperglycemia through increased glucose-dependent insulin secretion, glucagon suppression, delayed gastric emptying and appetite suppression." (PMID 25625935, 2015). "The administration of STZ leads to a rapid ablation of pancreatic β-cells, impairments in insulin production and subsequent hyperglycemia." (PMID 26197936, 2015). "Collectively, based on the current results we propose that impaired insulin signalling coupled with hyperglycaemia directly impedes sXBP1 activity in podocytes, thus exacerbating ATF6-dependent maladaptive ER response and DN." (PMID 25754093, 2015). "Proinsulin levels at 30 min and 120 min of an OGTT and proinsulin AUC 0–30 min were also significant predictors for the worsening of hyperglycemia and incident type 2 diabetes even after adjustment for insulin secretion." (PMID 25853252, 2015). "placebo: 61/393, P < 0.001), and the difference was mainly attributed to the increase of hyperglycemia requiring new insulin (steroid: 76/392 vs." (PMID 26374694, 2015). "It has been reported that berberine ameliorates hyperglycemia by enhancing insulin secretion, stimulating glycolysis, suppressing adipogenesis, and inhibiting mitochondrial function." (PMID 25705654, 2015). "STZ administration to rats promotes pancreas beta cell destruction and decreases the insulin secretion; therefore, the hyperglycemia in STZ-diabetic rats appears within 12–48 hours after STZ injection." (PMID 26064170, 2015). "ADMSC administration attenuated the hyperglycemia in 70% of diabetic treated mice and stimulated insulin production by pancreatic β cells." (PMID 25884215, 2015). "The common adverse events related to MK-2206 included rash, an elevated insulin c-peptide level, stomatitis, pyrexia, eosinophilia, leukopenia, and hyperglycemia." (PMID 26104654, 2015). "It is basically a group of metabolic diseases characterized by hyperglycemia and resulting from the defects in insulin secretion, insulin action or both." (PMID 28962370, 2015). "Specifically, HFD augments PAT morphological change, cytokine production and pancreatic damage in SENP1-aP2KO mice, and HFD augments hyperglycaemia and insulin reduction in SENP1-aP2KO mice." (PMID 26596471, 2015). "α-glucosidase inhibitors have been shown to be effective in suppressing postprandial hyperglycemia by limiting glucose absorption and the resulting insulin response." (PMID 25906471, 2015). "In the pathogenesis of diseases such as T2DM and metabolic syndrome, there is an increase in hepatic glucose production which results in hyperglycemia and an increased secretion of insulin leading to hyperinsulinemia." (PMID 26593941, 2015). "High use of insulin, recurrent hyperglycemia, hypoglycemia, and ketonuria were common during HEs management." (PMID 26455633, 2015).
Hyperglycemia (continued). "This indicates that L- and K-cell function was preserved in the patients, even though the resulting levels of GIP and GLP-1 were insufficient to elicit an appropriate insulin-secretory response in terms of controlling hyperglycaemia." (PMID 26567860, 2015). "The disease results from defects in insulin secretion, insulin action, or both, and it is characterized by a chronic hyperglycemia state." (PMID 26307962, 2015). "There is still a lack of clinical studies on the use of neutral protamine Hagedorn (NPH) and regular insulin (available in public health care system in Brazil) for inpatient treatment of hyperglycemia." (PMID 26697118, 2015). "We studied the effects of physiological insulin treatment in human umbilical vein endothelial cells (HUVECs) on the two pathways under high glucose conditions, which mimic the in vivo condition of hyperglycemia." (PMID 26297582, 2015). "The participants used anti-hyperglycemia drugs, including metformin, sulfonylureas, meglitinides, glitazones and insulin injections." (PMID 25849536, 2015). "Impaired insulin responses to Western meals exaggerate postprandial hyperglycemia and lipemia, creating a vicious cycle leading to vascular dysfunction and damage that, over time, likely augments risk for CVD." (PMID 26225995, 2015). "GPR40 (also known as a free fatty acid receptor 1) is highly expressed in pancreatic β-cells and mediates fatty-acid-induced enhancement of insulin secretion during hyperglycemia." (PMID 26561346, 2015). "Hyperglycemia-induced oxidative stress has been reported to inhibit the secretion of insulin in pancreatic beta cell through the activation of an uncoupling protein-2 (UCP-2) which lowers the ATP/ADP ratio by leaking protons in the β cell." (PMID 25821809, 2015). "In the case of persistent hyperglycemia, insulin was added, initially as a correction scale and then migrated to basal insulin if necessary." (PMID 28702223, 2015). "Whereas there is not a universally-accepted set of diagnostic criteria, most expert groups agree that this syndrome is defined by an endothelial dysfunction, an impaired insulin sensitivity and hyperglycemia, dyslipidemia, abdominal obesity and hypertension." (PMID 26198245, 2015). "Insulin is known to be secreted by pancreatic β-cells in response to hyperglycemia: its blood concentrations however exhibit both high-frequency (period approx. 10 minutes) and low-frequency oscillations (period approx. 1.5 hours)." (PMID 26555895, 2015). "Patients with only stress hyperglycemia are subjected to a gradual reduction in the dose of their IV insulin and finally stopped." (PMID 25874191, 2015). "So far, therapies have targeted insulin-sensitive organs such as muscles, liver and adipose tissue to improve hyperglycemia, hyperinsulinemia and resistance to insulin." (PMID 25759638, 2015). "There are some metabolic and genetic defects in the action or secretion of insulin which give rise to hyperglycemia in type 2 DM." (PMID 26273663, 2015). "GLUT1 expression is tissue-dependently regulated by circulating glucose levels, hypoxia, as well as hormones, including insulin and growth hormones, and it has been shown that chronic hyperglycemia increases RBC GLUT1 expression." (PMID 27239515, 2015). "Since blockade of SGLT2 promotes urinary glucose excretion and resultantly improves hyperglycemia in an insulin-independent manner, SGLT2 inhibitors are now one of the widely used agents for the treatment of diabetes." (PMID 26023321, 2015). "TG mice exhibited mild hyperglycemia, and insulin levels were also lowered in comparison to the wild-type animals." (PMID 26091000, 2015). "TZDs are PPARγ agonists used as antidiabetic drugs, whose mechanism of action induces a decrease in plasma free fatty acid concentrations and fasting hyperglycemia via an insulin-sensitizing effect." (PMID 26587016, 2015). "They showed that HemoHIM treatment reduced hyperglycemia, improved glucose tolerance, and increased blood insulin." (PMID 25883672, 2015).
Hyperglycemia (continued). "Type 2 diabetes (T2D) is a progressive metabolic disease characterized by hyperglycemia due to a combination of insulin resistance and defective insulin secretion." (PMID 26060824, 2015). "It is possible that other potential groups of microRNAs, which target IR (Tyr960) and IRS-1Ser307, counteracted the effects of miR-15b and miR-16 on the inhibition of insulin signaling in REC cultured in hyperglycemia." (PMID 25888955, 2015). "During transition from IV to SC insulin, basal dose needs to be reduced by 20–33% as the stress hyperglycemia is reduced and dose has to be adjusted accordingly." (PMID 25874191, 2015). "Recently, Dao’s group reported that human periosteum-derived progenitor cells derived insulin-producing cells ameliorate hyperglycemia in diabetic mouse model." (PMID 25629318, 2015). "In conclusion, the results demonstrate the ability of MSCs to promote prolonged decrease in hyperglycemia and apoptosis in pancreatic islets and increase in insulin sensitivity in HFD fed mice." (PMID 25923733, 2015). "Investigators at Standford reported that hyperglycemia in mice was associated with slower AAA enlargement, and this effect was diminished by insulin therapy." (PMID 25947103, 2015). "Still, treatment of T2D can only ameliorate hyperglycemia or temporarily improve the response to insulin in target tissues." (PMID 25923733, 2015). "The disease is characterized by hyperglycemia due to defects in insulin secretion and/or insulin action." (PMID 26432886, 2015). "After sacrifice of the mice, determination of serum insulin and blood glucose showed that MG induced marked hyperinsulinemia and hyperglycemia and indicated that these diabetic features were improved by co-administration of pioglitazone or resveratrol." (PMID 25884658, 2015). "Administration of mATG in combination with a subcutaneously implanted insulin pellet to spontaneously diabetic NOD mice resulted in durable remission from overt hyperglycemia in 40% of treated mice (4 out of 10), confirming our previous findings." (PMID 26580221, 2015). "The maximal insulin secretory response of the β cell depends on hyperglycaemia and exposure to arginine." (PMID 26567860, 2015). "Due to the decreased survival beta cell in pancreas, insulin secretion was also decreased leading to the decreased glucose uptake into peripheral tissues and finally resulting in hyperglycemia." (PMID 25969689, 2015). "The same authors observed that ‘fasting type’ hyperglycemia is associated with greater body mass index, higher serum triglyceride, hs-CRP and ALT levels at baseline, and more weight gain after treatment with insulin." (PMID 25874190, 2015). "Important CHD biomarkers which have been noted to change with chronic consumption of HGL diets are hyperglycaemia as represented by changes in the glycated haemoglobin levels and hyperinsulinaemia as represented by increased serum insulin levels." (PMID 25774201, 2015). "Given that hyperglycemia is a component of the MetS and most individuals with MetS are insulin-resistant, it is often considered a prediabetic state." (PMID 26064978, 2015). "Control of hyperglycemia with luseogliflozin or insulin significantly reduced the increase in kidney weight compared to that seen in rats treated with vehicle alone." (PMID 26169541, 2015). "This rise is the response of pancreas to hyperglycemia by enhancing the proliferation of pancreatic β-cells and their ability to secrete insulin." (PMID 26568772, 2015). "On day 3 the blood insulin level was 0.12 μUI/mL and C peptide was <0.1 ng/mL during an episode of hyperglycemia (312 mg/dL)." (PMID 26770845, 2015). "A low ratio suggests a greater contribution of the fasting component of hyperglycemia, and supports the use of basal insulin." (PMID 25874190, 2015).